SOCS1 (suppressor of cytokine signaling 1)
Diseases named in the same sentence as SOCS1 in open-access papers (continued):
Sharing a sentence is not in itself a finding about the gene and the disease.
tumor (continued). "However, it is possible that SOCS1 expression in tumor cells also regulate antitumor immune responses in a cell-extrinsic manner via direct and indirect mechanisms." (PMID 38415248, 2024). "This study provides insight into the tumor suppression mechanisms of SOCS1." (PMID 38254783, 2024). "However, the knockdown of the SOCS-1 gene in macrophages enhances anticancer inflammation and reduces tumor development." (PMID 38482001, 2024). "Notably, SDHA (succinate dehydrogenase complex subunit A), a tumor suppressor that allows cells to grow in low oxygen conditions, was markedly downregulated by SOCS1." (PMID 38254783, 2024). "It is likely that the varied modulation of PRDX proteins by SOCS1 could be related to both redox regulation and tumor suppressor pathways." (PMID 38254783, 2024). "Validating these hypotheses will provide a compelling argument for the use of epigenetic modifying drugs to reverse SOCS1 gene repression to restore cell-intrinsic tumor suppressor functions as well as cell-extrinsic impact on antitumor immunity." (PMID 38415248, 2024). "The idea that SOCS1 expressed in tumor cells may influence the induction of antitumor immune response came from one of our unpublished observations." (PMID 38415248, 2024). "We propose that by promoting ubiquitin-dependent proteasomal degradation, SOCS1 expression in tumor cells can potentially increase antigen processing and presentation and thereby increase the efficiency of the cross-dressing pathway and promote antitumor immunity." (PMID 38415248, 2024). "Moreover, SOCS1 expressed in mesenchymal cells can inhibit tumor promoting inflammatory cytokine signaling that establishes a tumor-promoting microenvironment." (PMID 38415248, 2024). "Hence, controlling the oxidative stress response is an important tumor suppression mechanism of SOCS1." (PMID 38254783, 2024). "Interestingly, SOCS1 also acts as a tumor suppressor and is therefore silenced in many different tumor entities." (PMID 39840313, 2024). "The tumor suppressor function of SOCS1 can be attributed to various mechanisms, which may operate in various combinations in diverse cancers in a context-dependent manner." (PMID 38415248, 2024). "In the human HCC70 BC cell line, NORAD seems to work as a tumor suppressor through its capability to sponge miR155-5p, which leads to the positive regulation of SOCS1 and a reduction in cell proliferation, migration and invasion behavior in vitro, affecting overall BC progression." (PMID 38339387, 2024). "However, upon further analysis of SOCS1 expression at different pathological stages, there was an increase in SOCS1 expression in the initial stages of tumor progression." (PMID 39414916, 2024). "Notably, SOCS1 acts as a tumor suppressor by facilitating the degradation of oncoproteins, inhibiting cell proliferation and apoptosis." (PMID 38339387, 2024). "A fundamental role of SOCS1 is its role as a tumour suppressor." (PMID 39676878, 2024). "SOCS1’s interaction with various intracytosolic and intranuclear proteins also plays a role in cancer development, with altered expression observed in various tumor entities." (PMID 38711523, 2024). "Thus, a key tumor suppression mechanism of SOCS1 is to prevent the tumor suppressors SOCS3 and CDKN1A from gaining oncogenic potential." (PMID 36765862, 2023). "In addition, the promoter activity of SOCS1 was positively regulated by PRDM5, implying the possible mechanism underlying the tumor suppressive activities of PRDM5 in LUAD cell proliferation." (PMID 36127737, 2023). "One such potential pathway is IFNγ-mediated upregulation of SOCS1 in tumor cells." (PMID 37711623, 2023).
tumor (continued). "Loss of SOCS3 in SOCS1-deficient mice reduced the growth of DEN-induced HCC without affecting tumor incidence." (PMID 36765862, 2023). "This may be due to SOCS1 expression could be related to the abundancy of tumor cells that pretreatment display the DTP state." (PMID 37916165, 2023). "Interestingly, according to the data analyzed, the expression of SOCS1 is lower in the tumor tissue than in normal adjacent tissue." (PMID 37916165, 2023). "An additional tumor suppressor mechanism of SOCS1 could be the attenuation of the oncogenic potential of CDKN1A." (PMID 36765862, 2023). "Taken together, our findings identified CASC2 as a tumor suppressor to inhibit HCC development by regulating the miR-155/SOCS1 axis, and CASC2 might be a potential therapeutic target of HCC for future clinical treatment." (PMID 36816357, 2023). "In addition, KIAA0087 overexpression led to a decreased miR-411-3p expression level and an increased SOCS1 expression level in tumor tissues." (PMID 37009803, 2023). "Downregulation of SOCS1 in OS tumor tissues were validated by RT-qPCR assay." (PMID 37009803, 2023). "Functionally, these results confirmed that CASC2 could function as a tumor suppressor by acting as a ceRNA to bind to miR-155 and downregulate the expression of SOCS1." (PMID 36816357, 2023). "Thus, the function of SOCS1 can be either tumor‐suppressive or oncogenic and is dependent on tissue milieu." (PMID 35137551, 2022). "Proteins DAPK1 (Death-associated proteinkinase 1), MGMT (Methylated-DNA-protein-cysteine methyltransferase),and SOCS1 (Suppressor of cytokine signaling 1)are considered tumor suppressors, and their low expressionin carcinomas correlates with disease progression." (PMID 36714033, 2022). "SOCS1 is also considered to be a tumor suppressor in many cancers and may act as a tumor suppressor or promoter in a manner that depends on the cell environment." (PMID 36199788, 2022). "Importantly, loss of the tumor suppressors STAT1 and SOCS1 appoint to loss of inhibitory functions and loss of negative feedback control." (PMID 36341492, 2022). "Cells without STAT1 gene cannot be induced to produce SOCS1 due to IFNγ signalling pathway obstruction, which may induce malignant cell proliferation, thus SOCS1 is also regarded as a tumor inhibitor." (PMID 36185620, 2022). "SOCS1, CD274, and SOX11 associated with miR-155 and miR-215 in the regulation hub suggested exerting vital functions in tumor immunology, whether through the miR-155, miR-215 pathway or not." (PMID 35433461, 2022). "SOCS1 has also been shown to have a role in tumor progression in CRC." (PMID 35137551, 2022). "SOCS1 is a unique tumor-suppressor gene that regulates inflammation-related tumorigenesis." (PMID 36505769, 2022). "Interestingly, changes in SOCS1 expression through altered DNA methylation levels in tumor cells are well-characterized; however, complex phenotypes are observed with these changes." (PMID 36439639, 2022). "However, SOCS1 methylation, either in CpG islands or promoter regions, was reported to be correlated with tumor growth and tumor size in HCC." (PMID 34679523, 2021). "In addition, treatment with tumor cell-conditioned media was shown to upregulate SOCS1 to suppress DC maturation." (PMID 34604264, 2021). "Furthermore, SOCS1 silencing in macrophages also suppressed tumor development due to enhanced anti-tumor inflammation." (PMID 34604264, 2021). "Methylation of several tumor-related genes, including MINT17, MINT31, TFPI2, WIF1, RASSF1A, and SOCS1, comprising the first melanoma CIMP, increased significantly with advanced clinical stages, suggesting that their inactivation is associated with tumor progression." (PMID 34944843, 2021). "In contrast, adenovirus delivery of SOCS1 was shown to enhance T cell-mediated anti-tumor immunity." (PMID 34604264, 2021).
tumor (continued). "SOCS1 is a gene with known regulatory functions in autoimmunity and a tumor suppressor in cancer." (PMID 34874980, 2021). "It is easy to imagine that SOCS1 and NR4a act as immune checkpoints in tumor immunity." (PMID 34121041, 2021). "In summary (graphical abstract), we reveal that SPTBN1 functions as a tumor suppressor to stabilize SOCS1 protein, controlling the cellular level of p65 to suppress the expression of inflammatory cytokines, IL-1α, IL-1β and IL-6, and the expansion of MDSCs and Foxp3+Treg cells." (PMID 33754058, 2021). "SOCS1 could reduce inflammation within the tumor microenvironment to contribute to tumor suppression in a cancer cell-intrinsic manner." (PMID 33633568, 2020). "To gain a deeper understanding of the tumor suppressor functions of SOCS1 and SOCS3 in HCC, and to identify the signaling pathways that are aberrantly activated in the absence of SOCS1 or SOCS3, we carried out a systematic analysis on the TCGA dataset on liver HCC (TCGA-LIHC)." (PMID 32807134, 2020). "To determine whether SOCS1 can also inhibit tumours in vivo, we investigated the effect of SOCS1 on tumour growth in immunodeficient nude mice." (PMID 32096766, 2020). "SOCS1 methylation may be used as a tumour suppressive factor in HCC, as similar reports observed this phenomenon in a variety of other tumours." (PMID 32096766, 2020). "Instead, tumor growth retardation shown in mice bearing tumors derived from LINC00669-deficient CNE-2 cells was completely reversed in the recipients injected with LINC00669 and SOCS1 double knockdown cells." (PMID 32831137, 2020). "SOCS1 is a good indicator of prognosis, tumour size and long-term survival after resection." (PMID 32096766, 2020). "Because we observed increased tumor-infiltrating T cells in LLC-sh21 Socs1 KD tumors, as well as increased CD8+ T cell activation, we sought to identify cancer cell–intrinsic factors that could mediate these effects." (PMID 31133614, 2019). "On the other hand, other studies revealed SOCS1 tumour-suppressive functions in CRC." (PMID 31091767, 2019). "In addition, lentiviral vector (LV)-SOCS1-siRNA transduced DCs significantly enhance antigen-specific anti-tumor immunity." (PMID 30658461, 2019). "They found higher degree of methylation of MGMT, RARβ, RASSF1A, and CDH13 in tumour specimens and of SOCS-1 in peripheral blood with higher levels of IL-6, while others found less degree of methylation of USP2, TMEM49, SMAD3, DTNB, and IL-6 promoter with higher levels of IL-6." (PMID 31205673, 2019). "In BC cells, RNA interference silencing of SOCS1 recapitulates the oncogenic effects of miR-155, whereas restoration of SOCS1 expression attenuated the tumor-promoting function of miR-155, suggesting that miR-155 exerts its oncogenic role by negatively regulating SOCS1." (PMID 30602375, 2019). "Conclusively, these results demonstrated that CASC2 could exert as a tumor suppressive lncRNA in ESCC progression via regulating SOCS1." (PMID 31728180, 2019). "Overall, these results suggest that SOCS1 may have both protumour and antitumour activities, depending on the tumour genetic profile and the microenvironment." (PMID 31091767, 2019). "Indeed, silencing SOCS-1 in DCs enhanced antigen presentation, T cell priming, and anti-tumour immunity." (PMID 30717461, 2019). "SOCS1 functions as a tumor suppressor in PCa and its expression is reduced in PCa tissue." (PMID 30602375, 2019). "Among them, the suppressor of cytokine signaling (SOCS) family proteins, including SOCS1–7, which function as negative regulators or tumor suppressors to suppress cytokine‐mediated cell growth, play a key role in the termination of LR at the late phase after PH." (PMID 29729074, 2018). "However, the reason for decreased SOCS1 expression in tumor tissues remains incompletely understood." (PMID 30285793, 2018).
tumor (continued). "Interestingly, we found that SOCS1 expression significantly decreased in tumor tissues compared with corresponding adjacent tumor tissues and correlated with early recurrence (P<0.05)." (PMID 28661477, 2017). "The tumor samples from patient were analyzed for SOCS1 and 3 methylation status by MSP assay." (PMID 28404963, 2017). "SOCS1 can exert its anti-tumor functions through diverse mechanisms." (PMID 28235401, 2017). "Here, we found that SOCS1 silencing therapies may subsequently influence both the immunogenicity of the tumor as well the ability of the host to mount an effective immune response." (PMID 28079159, 2017). "Importantly, these data confirmed that miR-29a suppresses SOCS1 gene promoter demethylation and represses its expression, leading to cognate targets upregulation to promote tumor growth and metastasis." (PMID 28661477, 2017). "It suggests that SOCS1 inhibition may not only have effects on tumor cell properties, but also strongly regulates PD-L1 expression that could influence the tumor-induced immune response." (PMID 28079159, 2017). "In addition, the transfection of SOCS1 siRNA in DCs significantly enhances the immunogenicity of DC-based tumor vaccines to break self-tolerance and induces effective antitumor immunity." (PMID 28228755, 2017). "Finally, our work further emphasizes the implication of SHP-1, SHP-2 and SOCS-1 genes as suppressors of tumor growth in different cancers." (PMID 28369102, 2017). "In summary, SOCS1 is lowering colony forming capacity of primary murine BM cells under pro-proliferative conditions, while it protects cells from the effects of anti-proliferative cytokines indicating the potential tumor suppressive but also oncogenic function of SOCS1." (PMID 28753604, 2017). "In this study, we found SOCS1 methylation are correlated with tumor grade and TNM stage." (PMID 28404963, 2017). "However, formation of metastasis was blocked by the presence of SOCS1 in the SOCS1/BCR-ABL group supporting a tumor suppressive role for SOCS1." (PMID 28753604, 2017). "On the other hand, several studies suggested pro-tumor functions of SOCS1." (PMID 27613835, 2016). "Consistent with an enhanced M1 phenotype, deficiency of SOCS1 in macrophages rendered LysM-cre-Socs1fl/fl mice resistant to B16 melanoma cell implantation and protection from dextran sulfate sodium (DSS)-induced tumor formation in the colon." (PMID 26579124, 2015). "Another example of enhanced M1 responses in the absence of SOCS3 in macrophages in vivo is protection from tumor transplantation and metastasis, similar to macrophage-specific SOCS1 deficiency." (PMID 26579124, 2015). "Thus, the SOCS1 mutation status in HRS cells represents a novel, tumor cell-derived, single gene prognostic biomarker in cHL." (PMID 26336985, 2015). "miR-29b targets de novo methyltransferases DNMT3A and DNMT3B mRNAs and reduces global DNA methylation in MM cells and therefore could restore expression of tumor suppressor genes silenced by hypermethylation such as SOCS1." (PMID 24991558, 2014). "In HCCs, approximately 65% of primary tumours showed abnormal SOCS1 methylation in exon 2 and restoration of SOCS1 expression suppressed cell growth and resulted in apoptosis, and the methylation frequency of SOCS1 gene was 82.6% in a cohort of 115 human HCC samples." (PMID 24757565, 2014). "DNA methylation changes significantly during disease progression and could silence important tumor suppressor genes including SOCS1." (PMID 24991558, 2014). "SOCS1 is one of the most frequently methylated genes (65%) in HCCs, and the deletion of SOCS1 in tumour cells might enhance IL-6-mediated cell proliferation." (PMID 24757565, 2014).
tumor (continued). "Additionally, miR-155 has been identified to suppress a number of tumor suppressors, including Socs1, which we found to be suppressed after genotoxic damage." (PMID 23496831, 2013). "On the multivariate analysis of the Cox proportional hazards model, miR-30d expression and tumor stage were statistically associated with biochemical recurrence (P = 0.003 for miR-30d expression, P = 0.004 for miR-30d and SOCS1 expression, and P = 0.036 for tumor stage)." (PMID 23231923, 2012). "Prophylactic intervention reversed tumor-suppressed phosphorylation or expression of STAT1 (1.82±0.20 vs. 0.46±0.10, p<0.001) and SOCS1 and suppressed the tumor-induced phosphorylation or expression of STAT3 (0.72±0.24 vs. 3.74±1.07, p<0.05) and SOCS3 in the lung tissues." (PMID 21931823, 2011). "Onthe other hand, the relationship between SOCS1 and other tumor suppressor pathways and the cellular mechanisms bywhich SOCS1 might exert its tumor suppression remain largely unexplored." (PMID 20622265, 2010). "Interestingly, some of these genes have been previously associated with CIMP in other tumor types, such as p73, GSTP1, SOCS-1, CACNA1G, CRABP1, NEUROG1 and RUNX3." (PMID 20830311, 2010). "Aberrant methylation was found in 65% of primary HCC tumour samples in SOCS1 gene." (PMID 17968429, 2007). "Moreover, methylation of SOCS-1 can be detected in about 30% of primary tumour tissues and 10% of adjacent normal tissues." (PMID 15354212, 2004). "Additionally, SOCS1 restricts the capacity of interferons (IFNs) to enhance tumor immunity." (PMID 38711523, 2024). "SOCS1 and SOCS3 proteins were initially described as onco-suppressors, being silenced in many tumors as consequence of hypermethylation of their promoters or mutations influencing proliferation, differentiation and survival of immune cells controlling tumor expansion." (PMID 38975347, 2024). "Indeed, the list of signaling proteins regulated by SOCS1 is so diverse that the SOCS1-dependent proteasomal degradation may have a fundamental anti-tumor function that is coupled to inhibition of the oncogenic signaling pathways." (PMID 38415248, 2024). "Interestingly, SOCS1 could reduce PD-L1 expression and restore the activation of tumor-infiltrating CD8+ T cells, which highlighted its potential as an immune checkpoint inhibitor in OV." (PMID 36386203, 2022). "Thus, SOCS1 functions as a tumor suppressor, and the inhibition of this function may promote cancer progression or relapse." (PMID 34527677, 2021). "To verify whether SOCS1 can also inhibit the proliferation of cancer cells in vivo, we injected SMMC-7721 stably overexpressing SOCS1 in immunodeficient nude mice, and the tumour volume and tumour growth rate of the SOC1 overexpression group were smaller than those of the control group." (PMID 32096766, 2020). "Moreover, we revealed that CASC2 functioned as a ceRNA of tumor suppressor SOCS1 against miR-155." (PMID 31728180, 2019). "In some tumor models SOCS1 may act either as a tumor suppressor gene or an oncogene." (PMID 28079159, 2017). "On the other hand, the over-expression of SOCS6 could be an epiphenomenon, constituting a negative feedback loop in response to multiple cytokine stimulation experienced by aggressive WM tumor cells, as described for SOCS1 in chronic myeloproliferative disorders." (PMID 28924457, 2017). "Therefore, SOCS1 is critical for the successful control of tumor dissemination." (PMID 28228755, 2017).